NEIL1 (nei like DNA glycosylase 1)
Diseases named in the same sentence as NEIL1 in open-access papers (continued):
Sharing a sentence is not in itself a finding about the gene and the disease.
cancer (continued). "To identify the mechanism underlying the reduction in NEIL1 and NEIL2 expression in cancer, we investigated whether these genes were epigenetically silenced in cancer using DNA methylation data from the TCGA database." (PMID 27042257, 2016). "A subset of the cancer types exhibited reduced NEIL1 and NEIL2 expressions and elevated NEIL3 expression, and such abnormal expressions of NEIL1, NEIL2, and NEIL3 were also significantly associated with the mutation loads in cancer." (PMID 27042257, 2016). "Human cells containing such NEIL1 or NEIL2 mutations are considered to have a reduced capacity to repair mutagenic bases; thus, similar to cancers with a reduced NEIL1 or NEIL2 expression levels, a higher incidence of mutation is likely to occur in the cells, leading to cancer susceptibility." (PMID 27042257, 2016). "Our studies showing the critical role of interactions among BER proteins suggest that these protein-protein interactions, typically involving a common binding interface, as in NEIL1, should be explored as a target to enhance chemo/radiation sensitivity of cancer cells." (PMID 23926464, 2012). "Presented interactions between Sirt3 and MUTYH, NEIL1, and APE1 in cancer cells and the effect of Sirt3 on the cellular response to oxidative stress indicate the necessity of Sirt3 for proper cell antioxidative reaction." (PMID 35440893, 2022). "All of those results indicated the importance of NEIL1 in BER pathway, however, we noticed that complications during cancer radiotherapy are also deserved our concern." (PMID 34105905, 2021). "Our results indicated that the downregulation of NEIL1 significantly inhibited the proliferation of CRC cells and slowed the cancer development." (PMID 32685496, 2020). "In this study, the 0.5-fold, 0.5-fold, and 2.5-fold values of the median expression value in noncancerous tissue samples of each organ were used as cut-off values to dichotomize the NEIL1, NEIL2, and NEIL3 expression values in the cancer cases, respectively." (PMID 27042257, 2016). "In conclusion, our study indicates that the abnormal expressions of NEIL1, NEIL2, and NEIL3 are likely to be involved in mutagenesis in human cancer." (PMID 27042257, 2016). "The total mutation loads were significantly higher in the group of cancers with the lower NEIL1 and NEIL2 expression levels in 4 of the 13 (30.8%) cancer types and 2 of the 13 (15.4%) cancer types, respectively." (PMID 27042257, 2016). "Furthermore, by resorting to several recent review articles, there were 26 RESs with cancer‐related clinical significance that were covered by our dataset, which resided in 7 genes (AZIN1, BLCAP, COG3, COPA, FLNB, GRIA2, and NEIL1)." (PMID 34319007, 2021). "SNPs of backup 8oxoG pathways such as PNK/NEIL1 have been linked to HNSCC risk and contributes to poor survival in non-HNSCC cancer; however, the role of this pathway in relation to hOGG1 deficiencies has yet to be determined in HNSCC." (PMID 24364026, 2013). "However, some mechanistic aspects have not fully been clarified yet, e.g., NEIL1, NEIL2 and NEIL3 triple-knockout mice were not prone to cancer and do not have increased mutational frequency produced by defective BER." (PMID 32252452, 2020). "For example, mice lacking both OGG1 and MYH or NEIL1 and NTHL1 show strong cancer susceptibility." (PMID 28665322, 2017). "The effects of abnormalities in the DNA glycosylases NEIL1, NEIL2, and NEIL3 on human cancer have not been fully elucidated." (PMID 27042257, 2016). "The mouse mutants individually lacking OGG1, NTHL1, NEIL1, NEIL2, or MYH or cells derived from these mutants are viable and do not develop a strong phenotype, such as accelerated aging or enhanced incidence of spontaneous cancer." (PMID 28665322, 2017). "The levels of NEIL1 and NEIL2 mRNA expression in tumor tissue, compared with normal tissue, were significantly reduced in 6 of the 13 (46.2%) cancer types and 4 of the 13 (30.8%) cancer types, respectively." (PMID 27042257, 2016).
tumor (22 papers, 2008 to 2025). "Although overall mutation frequencies were elevated in NEIL1-deficient mice relative to wild-type mice, this increase was modest relative to the multifold increases in the tumor diameters." (PMID 38779538, 2024). "We performed differential expression analysis between high‐ and low‐expression groups of HFM1/NEIL1 in tumor samples with the median value as a cutoff in both datasets." (PMID 36708047, 2023). "An increase in edited NEIL1 levels can significantly impact the promotion of a tumour-inducing environment." (PMID 37845675, 2023). "We showed loss of the wild-type allele in tumours from carriers of ERCC5 c.2556A>G, NEIL1 c.248G>T; p.Gly83Asp or NTHL1 c.244C>T; p.Gln82Ter." (PMID 36969007, 2023). "Mechanistically, the high levels of ADAR1 increase A-to-I editing of miR-381-3p, a tumor suppressor miRNA that inhibits NF-kB signaling, as well as the editing of the DNA repair enzyme Endonuclease 8-like 1 (NEIL1)." (PMID 33430133, 2021). "Only NEIL1 gene was able to significantly distinguish tumour tissue from healthy tissue by both collection methods." (PMID 27383461, 2016). "This investigation demonstrated a modest aflatoxin-induced increase in the overall mutation frequency in NEIL1-deficient mice relative to repair-proficient mice, but without a change in spectra, while tumor frequencies and sizes were highly elevated." (PMID 38779538, 2024). "We observed that HFM1 and NEIL1 were downregulated in ESCC tumor tissues." (PMID 36708047, 2023). "Tumour DNA from ERCC5, NEIL1 and NTHL1 variant carriers exhibited loss of the wild-type allele." (PMID 36969007, 2023). "However, we observed no LOH in tumour DNA from one carrier each of ERCC5 or NEIL1 variants and two carriers of NTHL1 variant." (PMID 36969007, 2023). "The expression levels of two DDR genes, HFM1 and NEIL1, were downregulated in ESCC tumor tissues and had an independent effect on the infiltration of mast cells." (PMID 36708047, 2023). "Endonuclease 8-like 1 (NEIL1) is another substrate that undergoes hyper-editing by ADAR1, and its clinical significance in tumour development has been established." (PMID 37845675, 2023). "Further investigation illustrated that DNMT1/3A/3B, TDG, SMUG1, UNG, NEIL1, MDB3/4, ZBTB33, and UHRF1/2 were essentially upregulated in tumor samples, while TET2, MBD1, and MBD2 were downregulated in tumor samples." (PMID 35205097, 2022). "Hypermethylation of the DNA glycosylase NEi endonuclease VIII-like 1 (NEIL1) promoter has been demonstrated in HNSCC, with increased methylation levels in tumors compared to matched non-tumor cells." (PMID 36338767, 2022). "In contrast, NEIL1, another DNA BER enzyme, was present as a single band in both tumor and adjacent normal tissues from NSCLC patients." (PMID 26981776, 2016). "We observed that in hospital A, there were 2 genes (NEIL1 and XPA) with differential expressions (tumour versus healthy adjacent tissue) collected in PAXgene Tissue System." (PMID 27383461, 2016). "In the same hospital, significantly different expressions between matched tumour and healthy adjacent tissues were observed for 6 genes (APEX1, DDB1, ERCC1, NEIL1, PARP1, RPA2) after snap freezing collection." (PMID 27383461, 2016). "Seven genes out of 13 (CCNH, ERCC2, ERCC6, NEIL1, OGG1, RPA1, XPA) had a significantly different expression in tumour versus normal tissue stored in PAXgene Tissue System." (PMID 27383461, 2016). "Analysis of B- and plasma cells (26,156 cells) showed that germinal centre (GC) B-cells (RGS13+, NEIL1+), cycling B-cells (UBE2C+, TYMS+) and naïve B-cells (TCL1A+, IL4R+) were all enriched in HPV+ve tumours compared to HPV-ve tumours, while switched B-cell subsets were found in both." (PMID 39757146, 2025). "Interestingly, NEIL1, RAD52, and POLD4 showed overexpression in the adjacent mucosa compared to tumor tissue." (PMID 41275076, 2025). "Meanwhile the NEIL1 protein expression level was significantly lower in the tumor tissues than in the nontumor tissues." (PMID 34105905, 2021).
tumor (continued). "The DNA repair activity of multiple lesion-specific DNA glycosylases, such as MPG, SMUG1, UNG, NTH1, NEIL1 and OGG1 could be readily detected in lysates from human tumor cells (LN428, U2OS and K562 cell lines) and normal cells (PBMCs)." (PMID 30167090, 2018).
infection (3 papers, 2011 to 2020). The state of being infected such as from the introduction of a foreign agent such as serum, vaccine, antigenic substance or organism. "Inaddition, infection of NEIL1 null MEFs indicates that this glycosylase plays asimilar role in the HIV life cycle." (PMID 21448273, 2011). "Deletion of the Neil1 glycosylase gene also led to significant decreases in HIV (P<0.0001) and FIV (P = 0.0003) infection compared to wild type cells." (PMID 21448280, 2011). "Neil1 null cells did show a significant decrease in MMLV infection (P = 0.004), but the infection efficiency was less than 30% different from wild type cells." (PMID 21448280, 2011). "Similar to human EDMs, Fn infection led to the downregulation of NEIL2 and NEIL1 transcripts." (PMID 32872214, 2020).
neurodegenerative disease (2 papers, 2019 to 2022). A disorder of the central nervous system characterized by gradual and progressive loss of neural tissue and neurologic function. "Our results support the observation that neural tissue is particularly vulnerable to Neil1-deficiency in adults and is linked to neurodegenerative disease." (PMID 31566562, 2019).
NEIL1 also shares sentences with these, for which no sentence is quoted: fatty liver disease (5 papers); adenoma (2); ischemic stroke (2); lung adenocarcinoma (2); acute lymphoblastic leukemia (1); Autoimmunity (1); B-cell acute lymphoblastic leukemia (1); Cerebral ischemia (1); cervical intraepithelial neoplasia (1); cervical squamous cell carcinoma (1); clear cell renal cell carcinoma (1); colon adenocarcinoma (1); colorectal adenoma (1); desmoid tumor (1); diabetes (1); fibrosarcoma (1); glioblastoma (1); head and neck cancer (1); hereditary cancer (1); Hyperinsulinemia (1); Insulin resistance (1); keratoconus (1); liver cancer (1); lung squamous cell carcinoma (1); Lynch syndrome (1); melanoma (1); metabolic disease (1); multiple sclerosis (1); Onset (1); ovarian serous cystadenocarcinoma (1).
A further 7 diseases each share a sentence with NEIL1 in 1 paper.